IL1B (interleukin 1 beta)
Diseases named in the same sentence as IL1B in open-access papers (continued):
Sharing a sentence is not in itself a finding about the gene and the disease.
epilepsy (continued). "Moreover, after tonic–clonic seizures, in vivo studies indicated an elevated production and secretion of proinflammatory cytokines like IL-1β, IL-6, and TNF-α in cerebral spinal fluid (CSF) and blood serum in patients with epilepsy." (PMID 30922332, 2019). "Based on the reported IL-1ß involvement in the epilepsy models and the potential predictive value this cytokine could have for PTE, this study focus was to determine the possible role of IL-1β in canine epilepsy and TBI." (PMID 31208341, 2019). "In all dogs with epilepsy, as well as in healthy dogs, IL-1β was not measurable in CSF using the described ELISA." (PMID 31208341, 2019). "Overexpression of several cytokines, including IL-1β and IL-8, has been previously reported in brain tissue, serum and CSF of patients with epilepsy, but data on saliva are lacking." (PMID 30344507, 2018). "IL-1β reduces GABA-mediated neurotransmission and inhibits Cl− outflow, which is mediated by GABA receptors, hence reducing the suppression of signal transduction mediated by GABA receptors that contributes to the occurrence of epilepsy in TLE patients." (PMID 30514296, 2018). "It has been demonstrated previously that seizures induce the upregulation of IL-1β and COX-2 in clinical specimens and experimental models of epilepsy; however, to reveal the main role of inflammatory molecules in epilepsy, further investigations are necessary." (PMID 26961169, 2016). "In our study we found a significant higher IL-1β expression in tumor tissue of patients with epilepsy and a significant (although weak) negative correlation with the expression levels of Kir4.1." (PMID 23270518, 2012). "qPCR demonstrated higher IL-1β mRNA expression in GBM with epilepsy compared to GBM without epilepsy." (PMID 23270518, 2012). "In the present study, we evaluated the expression of Kir4.1 and IL-1β in patients in relation to the presence or absence of epilepsy." (PMID 23270518, 2012). "Among the patients with epilepsy who were treated with levetiracetam, we found significantly higher expression levels of Kir4.1, and, conversely, lower expression of IL-1β, compared to patients who did not use this AED." (PMID 23270518, 2012). "For instance, a rapid activation of proinflammatory cytokines such as IL-1β, IL-6 and TNF-α was observed both in animal models of acquired epilepsy and in brain tissue obtained from patients with temporal lobe epilepsy or cortical developmental malformations undergoing epilepsy surgery." (PMID 39239395, 2024). "The authors of this study suggested a specific anti-inflammatory approach by blocking IL-1β biosynthesis, which may be helpful for managing this non-convulsive form of epilepsy." (PMID 37583518, 2023). "In addition, the level of intracellular IL-1β in peripheral monocytes, but not the serum, of pediatric drug-resistant epilepsy was higher than that of controls." (PMID 35054141, 2022). "However, this concept cannot be expanded to all epilepsies; using a rat model of audiogenic seizures, de Deus and colleagues reported similar levels of IL-6, IL-10, TNF-α and IL-1β between controls and experimental animals, but high correlation between seizure severity and nitrate levels." (PMID 35052661, 2022). "Therefore, we used the cytokines IL-1β, IL-18, and IL-6, which are all commonly found in neuroinflammation as inflammatory markers to explore the effect of treatment with GPR120-AAV-KD and GPR120-AAV-OE on neuroinflammation in epilepsy." (PMID 35624482, 2022). "This may be attributed to the reciprocal effects of epilepsy and PSD on these cytokines as clear from the decrease obtained in TNF-α during the chronic phase of the pilocarpine model and the increase in TNF-α, IL-6, and IL-1β in PSD animals." (PMID 33643575, 2021).
epilepsy (continued). "Additionally, there is in vitro and in vivo evidence that vitamin E can reduce neuroinflammatory responses mediated by microglial cells, including studies showing that treatment with alpha-tocopherol lowered hippocampal levels of IL-1β and TNF-α in an animal model of epilepsy." (PMID 34630015, 2021). "Unlike IL-1β, tumor necrosis factor-α exerts dual effects on epilepsy." (PMID 33597846, 2020). "However, the mechanisms by which IL-10 regulates IL-1β production and inflammasome activation in microglia with epilepsy have not been established." (PMID 30922332, 2019). "However, it is not clear how epilepsy augments inflammasome activation, and what the roles of IL-10 and IL-1β are in the process." (PMID 30922332, 2019). "Studies based on an epilepsy mouse model reproducing chronic human mesial temporal lobe epilepsy with sclerotic hippocampus (MTLE-HS), demonstrated that impairment of astrocyte gap junction coupling starts early (within 4 h after SE), and was induced by the presence of IL-1β, TNF and LPS." (PMID 29928494, 2018). "The postinjection images of rats to whom anti-IL-1β mAb-SPION was administered showed areas of negative enhancement (red arrow) in the regional zone of the brain lesion, in agreement with a significant decrease in T2 values by 21.5% in comparison to the preinjection image of epilepsy (P < 0.01)." (PMID 26925269, 2016). "The T2-negative enhancement in epileptogenic tissues of the MRI patterns performed before and after anti-IL-1β mAb-SPIONs injection confirms previous results showing that these functionalized magnetized particles were taken up by brain parenchyma and then crossed the BBB in this epilepsy model." (PMID 26925269, 2016). "Preclinical studies have shown that pathways such as the Bcl-2, IL-1β, NT-3 and the MAPK pathway that are also involved in miRNA dysregulation may also be promising new horizons for diagnosis and treatment of experimental as well as clinical epilepsy." (PMID 26528124, 2015). "In addition, in order to detect changes in Kir4.1 expression and/or localization in tumor astrocytes and their relationship to IL-1β expression and to the tumor epileptogenicity, astrocytic tumors with and without epilepsy were studied." (PMID 23270518, 2012). "Proinflammatory cytokines such as IL-1β, TNF-α and IL-6 have been shown to be overexpressed in experimental models of seizures, prominently by glia, suggesting that glia activation may contribute to vascular inflammation in epilepsy." (PMID 20863362, 2010). "Indeed, inflammatory mediators may be relevant for the pathogenesis of epilepsy in FCD, as confirmed by the reported up-regulation of inflammatory cytokines and their receptors and/or downstream effectors (such as IL-1β, IL-6, CCL3, CCL4, STAT3, C-JUN and CCR5) in this disease." (PMID 35741692, 2022). "Therefore, the present non-significant changes in IL-6 and IL-1β may be due to an adaptive mechanism in the chronic state of pilocarpine-induced epilepsy." (PMID 33643575, 2021). "Regardless of the role of the inflammatory system in epilepsy, it will be important to pursue the anticonvulsant and antiepileptogenic effects of the antagonists of shared mediators of inflammation and synaptic plasticity, including cyclooxygenase products, IL-1β, IL-6, and TNFα." (PMID 26464976, 2015). "Furthermore, research involving children with epilepsy demonstrated that treatment with valproate led to a significant decrease in serum levels of C–C motif ligand 2 (CCL2), a chemokine associated with inflammation, without altering levels of interleukin-1 beta (IL-1β)." (PMID 40507116, 2025). "Previously, we showed that IL-1β, TNF-α, and other proinflammatory mediators are overexpressed in VPA-resistant epilepsy, but we did not explore the mechanisms that trigger this phenomenon." (PMID 34497517, 2021).
epilepsy (continued). "In fact, IL-6, IL-1β, and MIP-1α levels were higher in the temporal cortex than in the hippocampus, and TNF-α showed no regional or epilepsy-related differences, though levels in entorhinal cortex may have been lower than either the hippocampus or temporal cortex." (PMID 27737716, 2016). "Because a relationship between epilepsy and inflammation has been established and inflammatory response in the pentylenetetrazole (PTZ)-seizure model has not been studied, we investigated the expression of the il1b and cox2 transcripts in zebrafish after seizures." (PMID 26961169, 2016).
liver fibrosis (263 papers, 2011 to 2026). "SWT collectively ameliorated liver fibrosis by inhibiting the COL8A1/IL-1β/OLR1 pathways associated with LSEC angiogenesis, adhesion and defenestration, as well as suppressing LSEC secretion of IL-1β to reduce HSC activation." (PMID 39741334, 2024). "The resolution of liver fibrosis is associated with a decrease in the levels of some cytokines, such as IL-6, IL-1-β, TNF, and TGF-β, in the liver." (PMID 39063116, 2024). "In a hyperglycemic state, the release of inflammatory factors such as IL-6, TNF-α, IL-8, and IL-1β can activate hepatic stellate cells and Kupffer cells, causing liver fibrosis, and can also stimulate cardiac fibroblasts, exacerbating myocardial fibrosis." (PMID 39775020, 2024). "Accordingly, macrophages and neutrophils constituting the liver fibrosis pathogenic cells are thought to release pro-inflammatory cytokines (IL-1β and TNF-α) upon activation [41." (PMID 36708488, 2023). "In the present study, prolonged inhibition of SIRT1 results in persistent activation of NLRP3 and triggers the production of pro‐inflammatory cytokines, such as IL‐1β, in age‐associated liver fibrosis." (PMID 36999514, 2023). "IL1B rs1143627 was also considered to be susceptibility alleles in individuals suffering from liver fibrosis infected by the hepatitis B virus." (PMID 36164436, 2022). "The expression of hepatic interleukin-1 beta (IL-1β) and collagen type IV, which are associated with liver fibrosis, were decreased with AT1 blockade." (PMID 36142809, 2022). "Anti-inflammatory action of autophagy in liver macrophages, such as Kupffer cells, involves limiting inflammasome activation and release of interleukin 1 beta (IL-1β) cytokine associated with liver fibrosis." (PMID 35252196, 2022). "Another study showed that mice with an IL-1β deficiency had less diet-induced inflammation and liver fibrosis." (PMID 33808318, 2021). "It is reported that the serum IL-1β in patients with liver fibrosis caused by schistosomiasis is significantly increased." (PMID 33790974, 2021). "Depending on the type of liver fibrosis driving infection, IL-1β can be one of the main factors underlying inflammation as in the case of chronic HBV infection, but not in chronic HCV infection." (PMID 32085494, 2020). "In the liver fibrosis caused by CCl4, the levels of mRNA encoding inflammatory factors F4/80, IL-6, IL-1β, and TNF-α reached a high value at 12 weeks." (PMID 33117360, 2020). "Certain IL-1β gene polymorphisms has been associated with liver fibrosis progression in primary biliary cholangitis and further confirm this eventuality." (PMID 30875826, 2019). "More recently, IL-1β was shown to be implicated in the transformation of steatosis to steatohepatitis and liver fibrosis." (PMID 30875826, 2019). "Inflammatory cytokines such as TNF-α, IL-6, and IL-1β are the main factors controlling the inflammatory response that causes liver damage and liver fibrosis." (PMID 28594374, 2017). "TNF-α, IL-6, and interleukin-1 beta (IL-1β) are proinflammatory cytokines that work in a vicious cycle with NF-κB signaling pathways to promote one another and intensify the inflammatory response, causing liver fibrosis." (PMID 40552161, 2025). "In addition, self-administration of CCl4 (Sham + CCl4 and PINX + CCl4 groups) to induce liver fibrosis caused a significant increase in the liver levels of IL-1β and IL-6 (p < 0.001) compared to the control and sham." (PMID 39007940, 2025). "In addition to inflammasome, IL-1β and gasdermin proteins are also important molecules that cause cirrhosis and liver fibrosis." (PMID 37081882, 2023). "Mice with IL-1β deficiency have reduced liver fibrosis and diet-induced inflammation." (PMID 34768813, 2021). "Additionally, as little as 50 mg/kg of HD is sufficient to alleviate liver fibrosis from several causes, including the inhibition of NF-κB/IL-1β/IL-10 and TGF-β/Smad2/3/CTGF signaling pathway and prevention of HSC activation." (PMID 32863858, 2020).
liver fibrosis (continued). "Previous studies have shown that the antifibrosis effect of a type of ginsenoside AD-2 extracted from ginseng on thioacetamide-induced liver injury in mice is related to the inflammatory factors (including TNF-α, IL-1β, caspase-1, and IL-6) associated with hepatic fibrosis." (PMID 32724321, 2020). "In the present study, we analyzed the effect of IL-1β alone or blocked with IL-1Ra on primary human HSCs, as well as the effect of IL-1Ra deficiency or supplementation in two models of in vivo experimental liver fibrosis." (PMID 30875826, 2019). "However, in the biological mechanisms underlie both renal and liver fibrosis, IL-1β, a pro-inflammatory mediator derived mainly by macrophages, endothelial cells, epithelial cells and fibroblasts seems to have a central role." (PMID 30616602, 2019). "Given that elevated inflammation due to TNF-α, IL-6 and IL-1β are amongst the causative factors of liver fibrosis and liver steatosis, and high levels of TNF-α, IL-6 and IL-1β are known to deregulate glucose metabolism, we measured the levels of these cytokines in the liver." (PMID 24260182, 2013). "IL1β is mostly related to the late stages of inflammation due to the recruitment of macrophages and could activate Kupffer cells, exacerbating the inflammatory response and causing liver injury and hepatic fibrosis." (PMID 40004960, 2025). "As reducing IL-1β may be associated with the suppression of inflammation, which may be predictive of hepatic fibrosis, this could account for the potential mechanism connecting IL-1β to hepatic fibrosis in patients with MAFLD." (PMID 39179677, 2024). "IL-1β could activate Kupffer cells and promote the conversion of hepatic stellate cells to myofibroblasts, further aggravating the inflammatory response, and causing liver injury and hepatic fibrosis." (PMID 36530698, 2022). "Hepatic fibrosis markers (Acta2 and Col1a1) and collagen deposition remained elevated in Tet2ΔMye-CCl4 mice despite IL-1β neutralization." (PMID 41474968, 2026). "To definitively exclude the regulatory role of the IL-1β–NLRP3 inflammatory axis in our liver fibrosis model, we administered an IL-1β–neutralizing Ab to CCl4-induced fibrotic mice." (PMID 41474968, 2026). "Initially, through network pharmacology, we predicted that the top three key proteins targeted by YQHX in alleviating liver fibrosis were IL-1β, IL-6, and TNF-α." (PMID 41296792, 2025). "Currently, extensive research is investigating strategies to mitigate the progression of liver fibrosis, including the use of receptor antagonists or the reduction of IL-1β and TNF-α levels in vivo." (PMID 41296792, 2025). "Polysaccharides extracted from Angelica sinensis root attenuated hepatic fibrosis by inhibiting IL-1β secretion and HSCs activation." (PMID 39995661, 2025). "We evaluated the following indicators by immunohistochemical staining to evaluate the degree of inflammation during liver fibrosis: IL-1β, IL-6, Antigen Ki67, and TNF-α." (PMID 40143016, 2025). "MCC950 an inhibitor of NLRP3 inflammasome activation, downregulated IL-1β expression and significantly reduced hepatic fibrosis." (PMID 39995661, 2025). "In mice with high-fat diet-induced nonalcoholic fatty liver disease (NAFLD), upregulation of IL-1β in hepatocytes contributes to increased fat aggregation, liver inflammation, insulin resistance and liver fibrosis." (PMID 39995661, 2025). "A meta-analysis encompassing 36,074 NAFLD patients and 47,052 controls showed that IL-1β was associated with NASH [odds ratio (OR) = 1.08, 95% CI = 1.01–1.15] and hepatic fibrosis (OR = 1.16, 95% CI = 1.04–1.29)." (PMID 40794228, 2025). "In alcoholic liver injury models using IL-1β-deficient mice, liver damage was significantly reduced, highlighting the regulator role of the IL-1β signaling pathway is steatosis, inflammation, and liver fibrosis." (PMID 39995661, 2025).